TRBV4-1 (T cell receptor beta variable 4-1)
Description:
V region of the variable domain of T cell receptor (TR) beta chain that participates in the antigen recognition. Alpha-beta T cell receptors are antigen specific receptors which are essential to the immune response and are present on the cell surface of T lymphocytes. Recognize peptide-major histocompatibility (MH) (pMH) complexes that are displayed by antigen presenting cells (APC), a prerequisite for efficient T cell adaptive immunity against pathogens. Binding of alpha-beta TR to pMH complex initiates TR-CD3 clustering on the cell surface and intracellular activation of LCK that phosphorylates the ITAM motifs of CD3G, CD3D, CD3E and CD247 enabling the recruitment of ZAP70. In turn ZAP70 phosphorylates LAT, which recruits numerous signaling molecules to form the LAT signalosome. The LAT signalosome propagates signal branching to three major signaling pathways, the calcium, the mitogen-activated protein kinase (MAPK) kinase and the nuclear factor NF-kappa-B (NF-kB) pathways, leading to the mobilization of transcription factors that are critical for gene expression and essential for T cell growth and differentiation. The T cell repertoire is generated in the thymus, by V-(D)-J rearrangement. This repertoire is then shaped by intrathymic selection events to generate a peripheral T cell pool of self-MH restricted, non-autoaggressive T cells. Post-thymic interaction of alpha-beta TR with the pMH complexes shapes TR structural and functional avidity.
Synonyms: TCRBV7S1A1N2T; TRBV41; TCRBV4S1; BV07S1J2.7
Tractability: Antibody: UniProt places it where antibodies can reach, with medium confidence; UniProt predicts a signal peptide or a membrane-spanning region; its Gene Ontology location is reachable by antibodies, with medium confidence.
Gene: T-cell receptor variable (V) gene on chromosome 7 (142,313,184 to 142,313,666, forward strand). Ensembl gene ENSG00000211710.
Subcellular location: Cell membrane
Gene Ontology:
Biological process: cell surface receptor signaling pathway
Cellular component: plasma membrane
Homologues: Orthologues: mouse Trbv5 (61% identical). Paralogues in human: TRBV4-2 (83% identical), TRBV3-1 (61% identical), TRBV23-1 (44% identical), TRBV5-4 (41% identical), TRBV12-5 (40% identical), TRBV18 (40% identical), TRBV5-1 (40% identical), TRBV5-6 (40% identical), TRBV5-5 (39% identical), TRBV9 (39% identical), TRBV12-4 (38% identical), TRBV16 (38% identical), and 39 more.
Diseases named in the same sentence as TRBV4-1 in open-access papers:
TRBV4-1 is named in the same sentence as 2 diseases in open-access papers, as found by Europe PMC text mining. Sharing a sentence is not in itself a finding about the gene and the disease. The quoted sentences say what the papers report.
tuberculosis (2 papers, 2022 to 2024). A chronic, recurrent infection caused by the bacterium Mycobacterium tuberculosis. "Biased usage of TRBV4-1 has been reported for CD1b-restricted T cells from blood and TB pleural effusions, suggesting that such TCRs are clinically relevant to host response in TB disease and could be biomarkers of M. tuberculosis infection." (PMID 39718834, 2024). "The hydrophobicity of CDR3 is changed in CD8+ T cells, and T cell receptor beta variable 4-1 (TRBV4-1) is preferentially expressed in TPE; the CD4+ T cell subpopulation may be important for protective immunity against tuberculosis." (PMID 36059506, 2022).
TRBV4-1 also shares sentences with these, for which no sentence is quoted: Pleural effusion (1 paper).